ROR1 (ROR family WNT receptor 1)
Diseases named in the same sentence as ROR1 in open-access papers (continued):
Sharing a sentence is not in itself a finding about the gene and the disease.
tumor (236 papers, 2009 to 2026). "Mechanistically, WNT5A, secreted by tumor-associated macrophages (TAMs) under hypoxia, activates ROR1-mediated Wingless-type MMTV integration site family (WNT) signaling in GSCs, promoting GDEC formation." (PMID 41562250, 2026). "In our experiments, the interaction of anti‐ROR1 CAR T‐cells with ROR1‐expressing tumor cells in the IAC model was associated with the release of proinflammatory cytokines, including TNF, IL‐6, and IFN‐γ." (PMID 40249196, 2025). "The activation of ROR1 has been associated with signaling pathways that are conducive to tumor growth, which has attracted interest as a potential anticancer target." (PMID 40762544, 2025). "Previous studies have reported the development of BiTEs against other tumor-associated antigens, including ROR1, EpCAM, and HER2, with encouraging efficacy across solid tumors." (PMID 41009508, 2025). "High ROR1 expression was associated with poorly differentiated and undifferentiated tumours (p < 0.001)." (PMID 41355329, 2025). "It has been observed that, in several cancers, ROR1 expression in tumor cells is linked to a dismal prognosis." (PMID 41339932, 2025). "In transgenic mouse models of spontaneous CLL, ROR1 signaling is associated with an increase in tumor proliferation and CSC self-renewal as well as an activation of pAKT." (PMID 40869147, 2025). "Elevated ROR1 levels were significantly associated with poor tumour differentiation (p < 0.001), lymph node metastasis (p = 0.007), and perineural invasion (p = 0.005)." (PMID 41355329, 2025). "Prior studies from our group demonstrated an association of ROR1-signaling with stem cell features, epithelial–mesenchymal transition, tumor proliferation, and metastases in preclinical models." (PMID 38408999, 2024). "ROR1-signaling is associated with epithelial–mesenchymal transition, tumor proliferation, and metastases." (PMID 38408999, 2024). "Our model uses CAR T-cells redirected against ROR1, a promising tumor-associated antigen (TAA) with a broad expression range in hematological malignancies and solid tumors." (PMID 37719008, 2023). "In the last few years, more attention has been paid to ROR1 because its elevated expression in many human neoplasms (breast, ovarian, lung) is associated with cancer development, progression, and metastasis." (PMID 36873868, 2023). "ROR1-specific antibodies or efflux pump inhibitors can reverse chemotherapy resistance and tumor recurrence caused by ROR1-induced ATP-dependent drug efflux pump (ABCB1) expression in BCs." (PMID 37457288, 2023). "In the tumour zone, we found the downregulation of ROR1, a molecule that has been associated with tumour progression and proposed as a therapeutic target in a number of cancers other than HNSCC." (PMID 35327656, 2022). "Analysis of tumor-infiltrating immune cells (TIICs) from GC showed that ROR1 was significantly associated with regulatory T cells (Tregs), natural killer T cells (NKT), Th17 cells, and M2-type macrophages in the tumor stroma of patients with GC." (PMID 34319035, 2021). "Overexpression of ROR1 is known to be closely associated with tumor growth, metastasis and chemotherapy resistance in several human tumor types." (PMID 33952725, 2021). "ROR1 expression was homogeneously distributed among the different tumor types, sorted by mutation status." (PMID 33172431, 2020). "ROR1 is also involved in maintaining the stemness of cancer cells, and is shown to be associated with disease progression and chemoresistance of various tumor cells." (PMID 32586008, 2020). "Our clinical observations, which were based on surface protein expression of ROR1, are in line with previous reports in various tumor types in which ROR1 was found to be associated with an inferior outcome." (PMID 32586008, 2020). "Among the clinical cohort (n = 360), ROR1 expression level was significantly associated with tumour grade (p = 0.013) and International Federation of Gynecology and Obstetrics (FIGO) stage (p = 0.030)." (PMID 32807831, 2020).
tumor (continued). "Targeting ROR1 not only will lyse ROR1+ tumor cells, but also cause toxicity on the ROR1+ normal tissues." (PMID 31429760, 2019). "We found that ROR1RCD137+ T cells had more effective anti-tumor activity than ROR1RCD28+ T cells in immune-deficient mice engrafted with ROR1+ tumor cells." (PMID 26030772, 2015). "ROR1 expression in tumor cells is linked to poor prognosis in several cancers." (PMID 39849645, 2025). "Corresponding mProtein expression was assessed using fluorescence‐labeled DLL3 antibody in DLL3/epithelial cell adhesion molecule (EpCAM)/receptor tyrosine kinase‐like orphan receptor 1 (ROR1)+ tumor‐associated EVs (tEV), captured with a mixture of DLL3, EpCAM, and ROR1 monoclonal antibodies." (PMID 40285610, 2025). "However, the association of ROR1 with metastasis and early relapse after therapy further underscores its role in driving tumor aggression." (PMID 40869147, 2025). "Through its association with poor differentiation, risk factors such as perineural invasion and desmoplasia, as well as metastasis formation, ROR1 may be viewed as a diagnostic marker for a higher aggressiveness of the tumour." (PMID 41355329, 2025). "In addition, elevated ROR1 was significantly associated with increased tumor grade and lymph node metastasis." (PMID 40869147, 2025). "Therefore, we selected this antibody combination for isolating DLL3/EpCAM/ROR1+ tumor‐associated EVs (tEV), as it provides superior performance across human samples." (PMID 40285610, 2025). "Second, high ROR1 expression in primary tumours is associated with lymph node metastasis formation." (PMID 41355329, 2025). "Src, a non-ROR1 implicated in tumor growth, represents a crucial factor in cancer biology." (PMID 41477115, 2025). "The expected ROR1 membranous/cytoplasmic staining pattern detected in all samples analyzed via IHC using clone 6D4 should reflect the presence of the expression of v1 and other variants in these tumour tissues as previously discussed by others." (PMID 39495778, 2024). "Suppression of Ror1 or Rif expression inhibited cell proliferation, survival, and invasion, accompanied by the loss of filopodia and cell polarity in vitro, and prevented tumor growth in vivo." (PMID 37703992, 2023). "This raises the question whether ROR1 is equally implicated in the regulation of EV cargo, and thus tumor EV uptake or adhesion, at pre-metastatic sites." (PMID 37430307, 2023). "Therefore, we determined the association of ROR1 with different types of TIICs in the tumor from GC patients using the EMTome database." (PMID 34319035, 2021). "ROR1 is expressed during embryonic development and in some normal tissues, but overexpressed in many incurable-stage, common solid tumors and is associated with poor prognosis possibly through regulating tumor growth and metastasis." (PMID 34332618, 2021). "Both YAP/TAZ and BMI-1 are regulators of self-renewal, differentiation, and tumor initiation of CSCs, indicating that glucocorticoids could induce ROR1-associated stemness phenotype in OC cells." (PMID 32989221, 2020). "Therefore, our study primarily focused on three intriguing tumour-associated antigens (TAAs), namely, receptor tyrosine kinase-like orphan receptor 1 (ROR1), trophoblast glycoprotein (TPBG/5T4) and carbonic anhydrase IX (CAIX)." (PMID 28687750, 2017). "Moreover, MDA-MB-231 cells silenced for ROR1 had relatively low expression of 70% of the CREB-bound genes in 29 of 49 genes contained with the 70 gene prognostic-signature associated with tumor specimens from patients with aggressive disease." (PMID 22403610, 2012). "However, the development of more specific anti-ROR1 antibodies has shown that this receptor is also expressed in normal human tissues such as parathyroid, pancreatic islets, and differentiated adipocytes, as well as in tumor-associated stroma cells." (PMID 37400436, 2023).
tumor (continued). "However, ROR1 is expressed in several malignancies including CLL and ROR1 has been considered a tumor associated antigen (TAA) belonging to the group of onco-fetal antigens which might be recognized by the patient’s immune system." (PMID 26562161, 2015). "ROR1 Ab-mediated active targeting enables precise tumor localization through NIR-II fluorescence imaging, and enhances chemotherapeutic efficacy while minimizing off-target toxicity." (PMID 41591256, 2026). "ROR1 expression is elevated in GDECs across patient-derived cells, xenografts, and tumor samples, confirmed by single-cell multiomics, Western blotting, and multiplex staining." (PMID 41562250, 2026). "In this field, the identification of ROR1 as a molecular target of several tumor types defines an opportunity for finding novel anticancer drugs." (PMID 40328670, 2025). "RMP-IL-18mutE4 enhanced mIFNγ-secretion (~10x EC50, ~2x Emax) from mouse splenocytes activated with anti-CD3, as well as mouse splenocytes co-cultured with ROR1+ tumor cells and redirected to recognize the tumor using the ROR1 T-cell engager." (PMID 41488627, 2025). "In conclusion, our results demonstrate the significant anti-tumor efficacy of the combination of oHSV C021 with anti-ROR1-CAR-NK cells targeting NB cells in vitro and in vivo." (PMID 39895691, 2025). "The data presented in this study further characterized the role of ROR1 in TNBC by identifying a novel function of ROR1 as an epigenetic regulator of tumor suppressors." (PMID 40427627, 2025). "Higher ROR1 expression was found in poorly differentiated and undifferentiated tumours compared to tumours with a higher degree of differentiation." (PMID 41355329, 2025). "In conclusion, this study evaluated ROR1 expression in a representative cohort of cSCC patients and revealed expression in the majority of tumour samples." (PMID 41355329, 2025). "Different treatment modalities including small molecule inhibitors, antibody‐based therapy and even CAR T‐cell therapy, have lately been proposed to target ROR1‐expressing tumour cells." (PMID 41355329, 2025). "ROR1 overexpression drives tumor progression, resistance to chemotherapies, disease recurrence, and ultimately metastasis." (PMID 40869147, 2025). "A significantly higher proportion of ROR1+ cells was observed in both D‐TGCT and L‐TGCT than in OA synovium, demonstrating that ROR1 was a specific marker of tumor cells for TGCT." (PMID 40126353, 2025). "KAN0439834, an inhibitor of the TK domain of ROR1, in combination with ibrutinib resulted in a significant increase in tumor death." (PMID 40869147, 2025). "Our results establish a pathway suggesting ROR1 as a potential therapeutic target for reversing the epigenetic silencing of tumor suppressor genes in TNBC and other malignancies that have low CREB3L1 expression." (PMID 40427627, 2025). "ROR1 promotes cancer cell proliferation, migration, and invasion, which are critical steps in tumor growth and metastasis." (PMID 40869147, 2025). "Doxycycline-induced inhibition of ROR1 in the PDAC cell line S2-VP10 decreases overall tumor growth, recurrence after chemotherapy, and metastasis to the lung and mesentery." (PMID 40869147, 2025). "The therapeutic potential targeting ROR1 in B-CLL tumor cell survival and proliferation has been validated in clinical trials." (PMID 41479906, 2025). "In most of the cancer types, ROR1 expression correlates with enhanced tumour growth and thus poor clinical outcome." (PMID 41355329, 2025). "In contrast, the majority of tumours from patients with lymph node metastases (17/27 cases) exhibited high ROR1 expression." (PMID 41355329, 2025). "This study aimed to evaluate ROR1 expression in cSCC and investigate its potential role as a biomarker for tumour aggressiveness." (PMID 41355329, 2025). "Combining ROR1 CAR-T cells with ferroptosis inducers enhanced anti-tumor efficacy in NSCLC by promoting ferroptosis through increased lipid peroxidation." (PMID 39849645, 2025).
tumor (continued). "While the signaling and clinical outcomes of ROR1 have been studied extensively in the total tumor population, its specific role in CSC biology remains poorly understood." (PMID 40869147, 2025). "Tumor cells treated with ferroptosis inducers showed increased sensitivity to Interferon gamma (IFN-γ) secreted by ROR1 CAR-T cells." (PMID 39849645, 2025). "The ROR-1-Src signaling pathway is a critical focus in tumor biology research, with implications for developing new cancer therapies." (PMID 41477115, 2025). "In patient populations with high DLEU2, lncRNA-driven ROR1 expression increased tumor proliferation and chemoresistance, dysregulated cell cycle progression and apoptosis, as well as enhanced metastatic characteristics and sphere formation." (PMID 40869147, 2025). "Our study has identified ROR1, a known oncogene, to be an upstream epigenetic regulator of a tumor suppressor, CREB3L1, in MDA-MB-231 and HCC1806 TNBC cell lines." (PMID 40427627, 2025). "Our findings indicate that the methylation of sites near the promoter region of the CREB3L1 tumor suppressor gene decreases when ROR1 is knocked down." (PMID 40427627, 2025). "Since ROR1 is upregulated in several malignancies, we propose further investigation into its role in the epigenetic silencing of tumor suppressors across various cancer types." (PMID 40427627, 2025). "To explore the mechanism by which RSL3 enhances tumor cell death following ROR1 CAR-T cell treatment, we harvested NCI-H1299 cells and performed lipidomic analyses." (PMID 39849645, 2025). "Of the 12 tumour samples with perineural invasion (3.3%), 10 exhibited high ROR1 expression, while only 2 samples with low ROR1 expression showed perineural invasion (p = 0.005)." (PMID 41355329, 2025). "In the following section we summarize the current understanding of ROR1 as a therapeutic target in CSCs for different tumor types." (PMID 40869147, 2025). "Given that the C57BL/6J mouse model can objectively reflect immune responses, these results indicate that ROR1 DAC treatment can engage T cells to suppress tumor growth, while PD-1 blockade further enhances antitumor activity." (PMID 39816690, 2025). "As a proof of concept, our study demonstrated that the dual blockade of the PD-L1/PD-1 and PD-L2/PD-1 axes enhanced the anti-tumor efficacy of ROR1-reactive T cells compared to monotherapies." (PMID 40723210, 2025). "Recent studies have demonstrated that ROR1 is upregulated in intestinal adenocarcinomas and correlates with aggressive tumor characteristics, including enhanced invasiveness and resistance to therapy." (PMID 40249196, 2025). "Most importantly, it was confirmed that ROR1-CAR-T cells penetrated deep into the tumor tissue and eliminated multiple layers of tumor cells." (PMID 40428391, 2025). "The results demonstrated a significant increase in tumor-infiltrating T cells in the ROR1 DAC, αmPD-1, and combination groups, with a notable increase in the combination group." (PMID 39816690, 2025). "This study revealed a significant increase in tumor mass in dynamic culture conditions and an initial spike in apoptosis induced by ROR1-CAR-T cells within the first 24 h of treatment, followed by a reduction in subsequent days." (PMID 40281554, 2025). "ROR1 expression was shown to be retained on 90%–95% of tumor cells after 22.0405.aF treatment, indicating that 22.0405.aF exposure does not significantly downregulate the percentage of ROR1-positive cells in these settings." (PMID 41479906, 2025). "In this last decade, scientific interest has been addressed toward ROR1 because of its critical role in tumor development." (PMID 40328670, 2025). "Meanwhile, the average tumor weight in the two ROR1 DAC dosage groups was significantly lower than that of the other groups." (PMID 39816690, 2025). "Consistent with the results from the PC3 xenograft mouse model, two doses of ROR1 DAC significantly inhibited tumor growth compared to the control groups." (PMID 39816690, 2025).
tumor (continued). "HTL lines recognized the ROR1403–417 peptide in a human leukocyte antigen (HLA)-DR-restricted manner, secreted effector cytokines, and exhibited direct cytotoxicity against ROR1+ tumor cells." (PMID 40723210, 2025). "This engineered CAR-T cell approach effectively eliminated ROR1-positive tumor cells in 3D tumors established from A549 (a non–small cell lung cancer) cell lines on a biological scaffold and an intact basement membrane." (PMID 39995659, 2025). "Cairo and colleagues developed a CAR NK cell targeting ROR1 and demonstrated the anti-tumor efficacy of the combination of an oncolytic virus engineered to secrete IL-21 (C021) with anti-ROR1-CAR-NK cells against NB." (PMID 39895691, 2025). "The further study explored the antitumor effects of ROR1-CAR-T cells in micro physiologic 3D tumor models of TNBC, specifically the MDA-MB-231 cell line." (PMID 40281554, 2025). "High ROR1 expression was detected in 42.5% of samples, predominantly localised at tumour invasive fronts." (PMID 41355329, 2025). "The importance of the ROR1-GRB2-c-FOS pathway is underscored by findings that artificial expression of c-Fos reverses the tumor-suppressing effects seen when ROR1 is silenced." (PMID 40869147, 2025). "We evaluated 22.0405.aF for ADCC activity and tumor-cell killing in comparison with clinically tested anti-ROR1 antibodies, including zilovertamab and R12." (PMID 41479906, 2025). "Regarding metastasis formation, we found that most tumours from patients with lymph node metastases exhibited high ROR1 expression in the primary tumour." (PMID 41355329, 2025). "We analysed ROR1 expression on primary tumour slides from a representative cohort of cSCC which consisted of mainly male patients with a mean age at diagnosis of 78.41 years." (PMID 41355329, 2025). "We leveraged an ROR1‐positive IAC model to study CAR T‐cell activity in a physiologically relevant tumor microenvironment." (PMID 40249196, 2025). "It systematically evaluates the results of studies targeting key tumor-associated antigens, such as EGFR, IL13Rα2, GD2, B7-H3, CEA, MSLN, PSCA/PSMA, and ROR1." (PMID 40969260, 2025). "GNC-035 targets CD3, 4-1BB, PD-L1, and ROR1 providing T-cell activation (CD3), co-stimulation (4-1BB), checkpoint inhibition (PD-L1), and tumor specificity (ROR1) within a single molecule." (PMID 40723181, 2025). "A study, performed recently, involving ROR1 CAR-T cells with inducible anti-PD-1 single-chain variable fragments (scFv) in TNBC models demonstrated enhanced tumor control, indicating a potential synergistic effect between PD-1 blockade and engineered T cells." (PMID 41249701, 2025). "ROR1 expression was heterogeneously distributed across the tumour samples, with high expression observed at the margins of tumour nests, particularly at the invasive front." (PMID 41355329, 2025). "Combining ROR1 CAR-T cells with ferroptosis inducers enhances anti-tumor efficacy in NSCLC by promoting ferroptosis through increased lipid peroxidation." (PMID 39849645, 2025). "The frequent convergence of oncogenic signaling pathways around ROR1 underscores its importance in mediating intracellular crosstalk and extracellular cues from the tumor microenvironment to drive this malignant phenotype." (PMID 40869147, 2025). "The data from this study establish a mechanism by which ROR1 regulates the methylation of key tumor suppressors in TNBC." (PMID 40427627, 2025). "The immunosuppressive effects observed in our study highlight the complex balance between CAR T‐cell efficacy and the tumor microenvironment, particularly in the context of ROR1‐expressing tumors." (PMID 40249196, 2025). "Tumor-associated antigens like MSLN, CEA, EGFR, ROR1, and c-Met are overexpressed in many solid tumors but often show low-level expression in normal tissues." (PMID 40969260, 2025).